AFTPH (aftiphilin)
Description:
Component of clathrin-coated vesicles. Component of the aftiphilin/p200/gamma-synergin complex, which plays roles in AP1G1/AP-1-mediated protein trafficking including the trafficking of transferrin from early to recycling endosomes, and the membrane trafficking of furin and the lysosomal enzyme cathepsin D between the trans-Golgi network (TGN) and endosomes.
Synonyms: MGC33965; FLJ20080; FLJ23793; Nbla10388
Tractability: PROTAC: ubiquitination databases record sites on it; its protein half-life has been measured.
Gene: Protein-coding gene on chromosome 2 (64,524,289 to 64,593,007, forward strand). Ensembl gene ENSG00000119844.
Subcellular location: Cytoplasm; Cytoplasm, perinuclear region; Cytoplasmic vesicle, clathrin-coated vesicle
Subcellular location (Human Protein Atlas): Cytosol; Golgi apparatus; Vesicles
Gene Ontology:
Molecular function: clathrin binding; protein binding
Cellular component: AP-1 adaptor complex; cytoplasm; cytosol; Golgi apparatus; trans-Golgi network membrane; clathrin-coated vesicle; perinuclear region of cytoplasm
Genetic constraint (gnomAD): Loss-of-function variants: 9 observed, 75.98 expected, observed/expected ratio (o/e) 0.12, 90% interval 0.07 to 0.21. The upper end of that interval is the gene's LOEUF score, 0.21, which puts it in group 1 of 6, group 1 being the genes least tolerant of losing a copy. Missense variants: 979 observed, 1,117.1 expected, observed/expected ratio (o/e) 0.88, 90% interval 0.83 to 0.92. Synonymous variants: 337 observed, 391.62 expected, observed/expected ratio (o/e) 0.86, 90% interval 0.79 to 0.94.
Homologues: Orthologues: chimpanzee AFTPH (99% identical), macaque AFTPH (97% identical), pig AFTPH (89% identical), dog AFTPH (89% identical), rabbit AFTPH (86% identical), mouse Aftph (79% identical), rat Aftph (78% identical), tropical clawed frog aftph (42% identical), zebrafish aftpha (32% identical), zebrafish aftphb (23% identical), Caenorhabditis elegans Y45G5AM.9 (12% identical). Paralogues in human: CLBA1 (7% identical).
Diseases named in the same sentence as AFTPH in open-access papers:
AFTPH is named in the same sentence as 12 diseases in open-access papers, as found by Europe PMC text mining. Sharing a sentence is not in itself a finding about the gene and the disease. The quoted sentences say what the papers report.
breast carcinoma (2 papers, 2020 to 2022). "AFTPH (Aftiphilin) was highly expressed in diffuse large B cell lymphoma, pancreatic adenocarcinoma, breast cancer, and lung squamous cell carcinoma and linked to poor prognosis." (PMID 36157883, 2022). "The results verified AFTPH overexpression in lymphoid, lung, abdominal, and breast cancer cell lines." (PMID 33090728, 2020).
pancreatic adenocarcinoma (2 papers, 2020 to 2022). "Here, we examined the expression profiles and prognostic significance of AFTPH in breast invasive carcinoma (BRCA), diffuse large B‐cell lymphoma (DLBC), lung squamous cell carcinoma (LUSC), and pancreatic adenocarcinoma (PADD) using the GEPIA and UALCAN databases." (PMID 33090728, 2020).
acute lymphoblastic leukemia (1 paper, 2023). Leukemia with an acute onset, characterized by the presence of lymphoblasts in the bone marrow and the peripheral blood. "Interestingly, the loss of AKAP12 and ZNF483 expression were described in prostate cancer and acute lymphoblastic leukemia, respectively; on the other hand, AFTPH was the most up regulated circRNA in our analysis." (PMID 37106694, 2023).
colitis (1 paper, 2020). Inflammation of the colon. "Law's studies indicated that activation of NT/NTR1 in colonic epithelial cells and colitis models could induce the expression of miR‐133α and reduce transcription of its downstream target AFTPH, which is involved in inflammatory signals in colonocytes and colitis models." (PMID 33090728, 2020).
ulcerative colitis (1 paper, 2022). An inflammatory bowel disease involving the mucosal surface of the large intestine and rectum. "The expression levels of aftiphilin (AFTPH) are significantly lower in inflamed colonic tissues from patients with ulcerative colitis (UC) and mice with experimental colitis." (PMID 41822093, 2022).
cancer (2 papers, 2020 to 2023). A tumor composed of atypical neoplastic, often pleomorphic cells that invade other tissues. "By collecting genetic information from CCLE, the investigation of AFTPH expression was extended to various cancer cell lines." (PMID 33090728, 2020). "Genetic alterations of AFTPH in cancers were explored using the cBioPortal website, revealing that gene copy number gains and amplification are common in BRCA, DLBC, LUSC, and PAAD." (PMID 33090728, 2020). "However, there are still several limitations to these results, and the molecular mechanisms governing the AFTPH‐related cancer pathway should be further elucidated." (PMID 33090728, 2020). "These genes and markers, which were either positively or negatively correlated with AFTPH expression, might be involved in the development of AFTPH‐related cancers." (PMID 33090728, 2020). "Therefore, we speculate that AFTPH, the newly discovered miR‐133α target, might play a role in cancer." (PMID 33090728, 2020). "Among these, AKAP12 and ZNF483 emerged as the most differentially down-regulated coding circRNAs whereas AFTPH, CHST15 and WDR37 were differentially up-regulated in the pan-cancer RNA-Seq dataset." (PMID 37106694, 2023). "However, the potential prognostic role of AFTPH in cancers remains unclear." (PMID 33090728, 2020). "AFTPH expression in cancer cell lines was investigated using the CCLE database; AFTPH was found to be highly expressed in four cancer cell lines." (PMID 33090728, 2020). "Furthermore, AFTPH overexpression in BRCA, DLBC, LUSC, and PAAD was reconfirmed in human cancer cell lines using CCLE." (PMID 33090728, 2020). "To date, no research has focused on AFTPH expression in human cancers." (PMID 33090728, 2020).
tumor (2 papers, 2013 to 2020). "The expression levels of AFTPH mRNA in tumor samples and corresponding normal samples were analyzed and compared using the GEPIA database." (PMID 33090728, 2020). "First, GEPIA database showed the expression differences of AFTPH between tumor samples and normal samples, suggesting that AFTPH was highly expressed in DLBC and PAAD than normal tissues." (PMID 33090728, 2020). "In addition, the expressions of AFTPH were explored in different tumor stages of BRCA, DLBC, LUSC, and PAAD." (PMID 33090728, 2020).
hematological malignancies (1 paper, 2020). "This study was the first to comprehensively analyze the expression profiles and prognostic role of AFTPH in solid tumors and hematological malignancies, as well as providing evidence for subsequent studies on the molecular mechanism governing this role." (PMID 33090728, 2020).
AFTPH also shares sentences with these, for which no sentence is quoted: breast invasive carcinoma (1 paper); diffuse large B-cell lymphoma (1); lung squamous cell carcinoma (1); prostate carcinoma (1).